LIN28A (lin-28 RNA binding posttranscriptional regulator A)
Diseases named in the same sentence as LIN28A in open-access papers (continued):
Sharing a sentence is not in itself a finding about the gene and the disease.
embryonal carcinoma (14 papers, 2009 to 2025). A non-seminomatous malignant germ cell tumor characterized by the presence of large germ cells with abundant cytoplasm resembling epithelial cells, geographic necrosis, high mitotic activity, and pseudoglandular and pseudopapillary structures formation. "Human LIN28A is encoded by the Lin28a gene, which is located on chromosome 1p36.11 and is mainly expressed in embryonic stem cells and embryonic carcinoma cells." (PMID 36831493, 2023). "Strong signals in embryonic carcinoma cells (PA-1) and hPSCs were observed only in the presence of both anti-UPF1 and anti-LIN28A antibodies, suggesting that UPF1 and LIN28A directly interact within the cells." (PMID 38167913, 2024). "Treatment of human embryonal carcinoma cells with NMM (100 μM for 48 h) led to accumulation of mature miRNA, decreased levels of pluripotency proteins corresponding to Lin28 mRNA targets (OCT4, HMGA1, CCNB1, CDK4, and Lin28A), and decreased levels of two Lin28 mRNA targets (MYC and Lin28)." (PMID 34385812, 2019).
pancreatic cancer (14 papers, 2013 to 2025). "Whether the LIN28A expression underlies epigenetic regulation mechanism remains to be clarified in pancreatic cancer cells." (PMID 26910839, 2016). "LIN28A enhances the characteristics of stem cells in pancreatic-cancer cells by inducing SOX2, OCT4, LIN28B, c-Myc, and NANOG." (PMID 37345019, 2023). "To assess the role of LIN28A in human pancreatic cancer cells, we further examined the abilities of invasion by transwell assays." (PMID 26910839, 2016). "Subsequently, LIN28A expression is increased at both mRNA and protein levels in pancreatic cancer cells treated with 5-Aza-2′-deoxycytidine (5-Aza-CdR), a DNA methyltransferase inhibitor." (PMID 26910839, 2016). "Herein, we identify that LIN28A is required for the differentiation of pancreatic cancer cells, and promotes their growth and invasion." (PMID 26910839, 2016). "We also found that LIN28A was critical for the stemness maintenance and invasion of pancreatic cancer cells." (PMID 26910839, 2016). "However, the LIN28A expression profile in pancreatic cancer cells is still unknown." (PMID 26910839, 2016). "In this study, we find that LIN28A increases the expression of stem cell markers SOX2, OCT4, LIN28B, c-Myc and NANOG in pancreatic cancer cells, and promotes their malignant behaviors including growth and invasion in vitro, further supporting the oncogenic potential of LIN28A." (PMID 26910839, 2016). "In contrast, Knocking down LIN28A resulted in the opposite effects in PANC1 cells, suggesting that LIN28A was significantly involved in the stemness maintenance of pancreatic cancer cells." (PMID 26910839, 2016). "Also, LIN28A overexpression resulted in upregulation of MMP2 and MMP9, while LIN28A knockdown downregulated the expression of MMP2 and MMP9 in PANC1 cells, indicating that LIN28A might be critical for invasion of pancreatic cancer cells." (PMID 26910839, 2016).
colon carcinoma (13 papers, 2012 to 2024). "Since the expression of both Lin28A and Lin28B is associated with colon cancer metastasis, we evaluated and compared the influence of both onco-proteins on the migration and invasion of HCT116 cells in vitro." (PMID 27793004, 2016). "LIN28A overexpression is associated with tumor progression in colon cancer." (PMID 28587210, 2017). "Additionally, we also observed the elevated expression of Lin28A in colon cancer, and found that Lin28A mRNA expression is associated with colon cancer metastasis." (PMID 27793004, 2016). "Consistently, the expression of LIN28A decreased upon knockdown of METAP2 in colon cancer cells, whereas this phenomenon was also abolished upon knockdown of Dicer." (PMID 33665193, 2021). "In this study, we confirmed that hypoxia increased the number and size of P-bodies in the colon cancer cells and that the relevant abundance of LIN28A mRNA in the P-bodies was also increased." (PMID 33665193, 2021). "Collectively, we demonstrated that LIN28A mRNA facilitates colon cancer metastasis in a protein-coding-independent manner." (PMID 33665193, 2021). "To determine the effect of hypoxia on LIN28A expression, we first examined the changes of LIN28A expression in colon cancer cells treated with DFO or cultured in 1% O2." (PMID 33665193, 2021). "In this study, we also confirmed the positive roles of LIN28A protein in the proliferation and metastasis of colon cancer cells." (PMID 33665193, 2021). "In this study, we examined the roles and molecular mechanisms of hypoxia in regulating the expression of LIN28A in colon cancer and explored the non-coding function and potential mechanisms of LIN28A mRNA in the progression of colon cancer." (PMID 33665193, 2021). "To explore the mechanism of hypoxia regulating LIN28A expression in colon cancer cells, we analyzed the promoter sequence of LIN28A gene and found several potential HIF1α binding sites." (PMID 33665193, 2021). "To investigate the underlying mechanism by which the non-coding LIN28A mRNA accelerates the colon cancer metastasis, we detected the expression change of protein profiles using MS after the over-expression of non-coding LIN28A mRNA in SW1116 cells." (PMID 33665193, 2021). "For colon cancer, we performed immunohistochemistry on 45 human tumor samples where 19 were LIN28A-positive while 14 expressed LIN28B." (PMID 28400788, 2017). "To learn the expression pattern of Lin28A and Lin28B in colon cancer, we initially detected the expression of both oncogenic proteins in 65 colon cancer tissues and 10 normal tissues using immunohistochemistry staining." (PMID 27793004, 2016). "In this study, we have found that the expression of Lin28A in colon cancer tissues is localized in the cytoplasm, which is consistent with previous study." (PMID 27793004, 2016). "The results showed that Lin28B protein is expressed in all the observed colon cancer tissues samples (positive rate is 100%), whereas Lin28A protein is expressed in 57 out of 65 samples (positive rate is 87.7%)." (PMID 27793004, 2016). "We previously found that Lin28A elevated expression enhanced the chemosensitivity of colon cancer cells to 5-Fu by promoting cell apoptosis in a let-7 independent manner." (PMID 27793004, 2016). "Additionally, we previously demonstrated that over-expression of Lin28A promotes the apoptosis of colon cancer cells induced by 5-Fu." (PMID 27793004, 2016). "For instance, several studies showed that Lin28B is overexpressed in colon cancer and promotes colon cancer progression, whereas the expression and functions of Lin28A in colon cancer are largely unknown." (PMID 27793004, 2016). "Additionally, the mRNA level of Lin28A instead of Lin28B in colon cancer patients with remote organ metastasis is significantly higher than that of patients with non-metastasis." (PMID 27793004, 2016). "And the result showed that the expression of neither Lin28A nor Lin28B is significantly associated with the prognosis of colon cancer patients." (PMID 27793004, 2016).
colon carcinoma (continued). "Consistently, our result of cell migration and invasion also demonstrated that both of Lin28A and Lin28B could promote the migration and invasion of colon cancer cells in vitro." (PMID 27793004, 2016). "The mRNA expression of both Lin28A and Lin28B was also analyzed in 162 colon cancer patients, and the results showed that the mRNA level of Lin28B is also significantly higher than mRNA level of Lin28A in colon cancer (P<0.01)." (PMID 27793004, 2016). "In this study, we have evaluated the co-expression of Lin28A and Lin28B in colon cancer tissues for the first time, and we showed that both oncogenes are expressed in colon cancer tissues, and the expression of Lin28B was significantly higher than the expression of Lin28A." (PMID 27793004, 2016). "Furthermore, we demonstrated that HIF1α binds to LIN28A in the colon cancer cells by ChIP assay." (PMID 33665193, 2021). "In this study, we have systematically evaluated the expressional pattern and correlation of both Lin28A and Lin28B in colon cancer tissues, and have determined and compared the roles of Lin28A and Lin28B in the proliferation, migration, invasion and apoptosis of colon cancer cells in vitro." (PMID 27793004, 2016). "Additionally, although the expression and role of Lin28B in colon cancer is frequently reported, the expression and functions of Lin28A in colon cancer are largely unknown." (PMID 27793004, 2016). "As expected, we showed that both miRNAs significantly targeted the expression of LIN28A and METAP2 in two colon cancer cell lines." (PMID 33665193, 2021). "Moreover, we detected the mRNA expression of LIN28A and METAP2 by using RT-PCR and revealed that the two were positively correlated with each other in 46 colon cancer tissues (r = 0.533)." (PMID 33665193, 2021). "In view of the fact that hypoxia only induced the mRNA expression of LIN28A, we hypothesized that the elevated LIN28A mRNA might promote the progression of colon cancer independent of its protein-coding function." (PMID 33665193, 2021). "Moreover, we showed that LIN28A protein but not LIN28A mRNA increased the Ki67 level in experimental metastatic colon cancer tissues, which is consistent with that LIN28A mRNA does not affect the proliferation of colon cancer cells." (PMID 33665193, 2021).
gastric cancer (13 papers, 2015 to 2025). A primary or metastatic malignant neoplasm involving the stomach. "These gastric cancers similarly exhibited the expression of Sall4 and Lin28a." (PMID 29802314, 2018). "Twenty-five gastric cancers that were diagnosed as AFP-producing gastric cancers, were examined for the expression of SALL4, LIN28A, and LIN28B by immunostaining." (PMID 29802314, 2018). "Consistently, human AFP-producing gastric cancers often co-express pluripotency-related proteins, such as SALL4, LIN28A, and LIN28B." (PMID 29802314, 2018). "Notably, as observed in gastric cancers in KC-OSKM mice, SALL4, LIN28A, and LIN28B were frequently co-expressed in human AFP-producing gastric cancers, suggesting that these cancers exhibit activation of the pluripotency-related regulatory network." (PMID 29802314, 2018).
liver cancer (12 papers, 2019 to 2025). An epithelial or non-epithelial malignant neoplasm that arises from the liver. "Previous studies have found that RNA binding protein Lin28A is a key factor of maintain the pluripotency of stem cells, and it is positively correlated with the degree of several cancers (breast, prostate, liver cancer, etc)." (PMID 30266988, 2019). "MSI2 promotes the stemness and chemoresistance in liver cancer stem cells via LIN28A activation." (PMID 31952541, 2020). "For example, LIN28A and LIN28B regulate the expression of genes, such as the transcription factor SREBP1, which is involved in the regulation of fatty acid synthesis, thus enhancing lipid accumulation and de novo fatty acid synthesis in liver cancer cells." (PMID 40265419, 2025). "Additionally, even though MSI2 target genes, such as MYC, LIN28A, and MET, have been extensively studied, the upstream mechanism driving MSI2 overexpression in liver cancer development remains unclear." (PMID 36599932, 2023).
germ cell tumor (11 papers, 2012 to 2024). A benign or malignant, gonadal or extragonadal neoplasm that originates from germ cells. "It has been reported that overexpression of LIN28A is associated with human germ cell tumors and promotes primordial germ cell (PGC) development from embryonic stem cells both in vitro and in vivo in mice." (PMID 27730721, 2017). "LIN28B expression is a poor prognostic factor in medulloblastoma, LIN28A is associated with worse prognosis in primitive neuro-ectodermal tumor, and LIN28A and LIN28B are known to be expressed in germ cell tumors." (PMID 25638158, 2015). "LIN28A is also emerging as an important factor in oncogenesis and a marker of germ cell tumors in humans." (PMID 22240064, 2012). "LIN28A is expressed in other CNS tumors, such as PNET, germ cell tumors and atypical teratoid rhabdoid tumors." (PMID 23846349, 2013).
glioma (11 papers, 2013 to 2025). A benign or malignant brain and spinal cord tumor that arises from glial cells (astrocytes, oligodendrocytes, ependymal cells). "Across glioma subtypes, LIN28A/B are overexpressed, let-7 family members are underexpressed, and let-7 family members antagonize a plethora of oncogene mRNAs to mediate glioma cell suppression." (PMID 37370851, 2023). "Of note, dysregulated expression and function of LIN28A/B and the let-7 family has been characterized in other pediatric non-glioma brain tumors, including embryonal tumor with multilayered rosettes, atypical teratoid rhabdoid tumor, and medulloblastoma." (PMID 37370851, 2023). "Downregulation of LIN28A also increases apoptosis and G1 phase cell count while decreasing S phase cell count and colony formation of glioma cells." (PMID 37370851, 2023). "Another important takeaway from this work was that LIN28A inhibition decreases invasion and growth of glioma cells." (PMID 37370851, 2023). "Lin28A was overexpressed in glioma tissues (as compared to NBTs), U87, and U251 cells (as compared to NHA)." (PMID 32527996, 2020). "LncRNA microarrays showed that SNHG14 was significantly downregulated in Lin28A-depleted glioma cells." (PMID 32527996, 2020). "We analyzed the expression and function of Lin28A, SNHG14, IRF6, GLUT1, and PKM2 and their underlying mechanisms in the tumorigenesis of glioma." (PMID 32527996, 2020). "In summary, the study provides novel insights into the role and function of the Lin28A/SNHG14/IRF6 axis in regulating glycometabolism in human glioma." (PMID 32527996, 2020). "The schematic cartoon of the mechanism of Lin28A/SNHG14/IRF6 axis functions as a potential aerobic glycolysis enhancer in glioma." (PMID 32527996, 2020). "Our results suggest that Lin28A is an oncogene that, when silenced, inhibits glycolysis, impairs proliferation, and enhances apoptosis in glioma cells." (PMID 32527996, 2020). "We detected LIN28A protein in a subset of human gliomas observed higher expression in glioblastoma (GBM) than in lower grade tumors." (PMID 23846349, 2013). "The experiments presented here indicate a role for LIN28A in the transformation of normal cells into aggressive glial tumors and an on-going requirement for LIN28A in GBM." (PMID 23846349, 2013). "Taken together, these data suggest a role for LIN28A in high grade gliomas and illustrate an HMGA2-associated, pro-invasive program that can be activated in GBM by LIN28A-mediated suppression of let-7 microRNAs." (PMID 23846349, 2013). "In glioma, LIN28A expression is increased, correlating directly with tumor grade and poor survival." (PMID 37370851, 2023). "Since PKM2 and GLUT1 are well-known regulators of glycolysis in tumors, we further investigate whether PKM2 and GLUT1 were involved in Lin28A-mediated reprogramming of glucose metabolism in glioma." (PMID 32527996, 2020). "Moreover, flow cytometry revealed that silencing Lin28A markedly increased apoptosis in the glioma cells." (PMID 32527996, 2020). "Lin28A is overexpressed and promotes the Warburg effect in glioma cells." (PMID 32527996, 2020). "Thus, we determined the expression and function of RNA-binding protein Lin28A, long noncoding RNA SNHG14, and transcription factor IRF6 in human glioma cells to elucidate the mechanism(s) underlying their role in glycolysis." (PMID 32527996, 2020). "Therefore, according to the literature above, we wondered whether Sox2, Oct4, KLF4, Nanog, Lin28A and Lin28B contribute to glioma cell dedifferentiation in hypoxic environments." (PMID 34976166, 2022). "In glioma cells, the Lin28A/SNHG14/IRF6 axis is pivotal for the reprogramming of glucose metabolism and the spurring of oncogenesis, and depletion of Lin28A reduced in vivo xenograft tumor outgrowth and prolonged nude mice survival." (PMID 34868981, 2021). "Taken together, our data revealed that the Lin28A/SNHG14/IRF6 axis is crucial for reprogramming glucose metabolism and stimulating tumorigenesis in glioma cells." (PMID 32527996, 2020).
glioma (continued). "This study reveals the oncogenic nature of Lin28A and SNHG14, while IRF6 functions as a tumor suppressor in glioma." (PMID 32527996, 2020). "Quantitative real-time polymerase chain reaction and western blotting showed that Lin28A and SNHG14 were overexpressed and IRF6 was downregulated in glioma." (PMID 32527996, 2020). "Therefore, we speculated that Lin28A might regulate SNHG14 in glioma cells." (PMID 32527996, 2020). "To further quantify LIN28A and LIN28B expression in high-grade gliomas, we expanded our evaluation of GBM to include The Cancer Genome Atlas (TCGA) dataset containing more than 500 GBM samples." (PMID 23846349, 2013). "Therefore, it is likely that similar to LIN28A, LIN28B increases proliferation and cell viability in glioma." (PMID 37370851, 2023). "There are two homologs of LIN28, LIN28A and LIN28B, both of which can be expressed in glioma cells." (PMID 34948433, 2021). "Single or combination therapy targeting Lin28A, SNHG14, and IRF6 has the potential in clinical settings and may help develop new therapeutic strategies for treating glioma." (PMID 32527996, 2020). "We hypothesized that interactions within the Lin28A/SNHG14/IRF6 axis may be responsible for reprogramming glucose metabolism, thereby stimulating the development and progression of glioma." (PMID 32527996, 2020). "Thus, Lin28A facilitated aerobic glycolysis by stabilizing SNHG14, thereby enhancing cell proliferation and impairing apoptosis in glioma cells." (PMID 32527996, 2020). "Since our results revealed the oncogenic nature of Lin28A and SNHG14 in glioma cells and the decrease in SNHG14 in the sh-Lin28A cells as compared to that in the sh-Lin28A-NC group, we speculated a positive correlation between SNHG14 and Lin28A." (PMID 32527996, 2020).
colorectal cancer (10 papers, 2013 to 2024). A primary or metastatic malignant neoplasm that affects the colon or rectum. "In colorectal cancer, exosomal‐transported circ_0067557 derived from CAFs can regulate Lin28 (including Lin28A and Lin28B), which enhances proliferation, metastasis, and chemoresistance of tumor cells." (PMID 39584047, 2024). "For example, in a study on colorectal cancer, LIN28A was found to promote the development and progression of disease by regulating the expression of the mRNA GEFT." (PMID 34868981, 2021). "Additionally, by binding to LINC00355 or GEFT 3’UTR, LIN28A moderated LINC00355-mediated GEFT expression, increased GEFT mRNA stability, and facilitated colorectal cancer formation, development, and aggression." (PMID 34868981, 2021).